TNF (tumor necrosis factor)
Diseases named in the same sentence as TNF in open-access papers (continued):
Sharing a sentence is not in itself a finding about the gene and the disease.
myocarditis (continued). "Moreover, the cytokine levels of TNF-α, IL-1β, and IL-18 were significantly reduced in LQF group, suggesting that LQF can alleviate myocardial inflammation induced by MI, thereby improving the cardiac function." (PMID 35310035, 2022). "The patients with myocarditis also showed high levels of IL-1 receptor antagonist (interleukin 1), IL-5, and IL-16 but no proinflammatory cytokines, for example, IL-6, tumor necrosis factor, IL-1B, IL-2 or interferon-γ." (PMID 36498573, 2022). "In these models, mice with fulminant myocarditis seemed to have a marked elevation of cytokines with negative inotropy-like interferon-γ and tumor necrosis factor-α." (PMID 35208538, 2022). "The association between TNF-α inhibitors and progressive heart failure does not seem to be relevant in patients with ICI-induced myocarditis." (PMID 35844550, 2022). "In animal models, IL-1 has been determined to be non-essential for the development of acute myocarditis, which is driven by TNF in the acute phase of KD, but plays an essential role in the subsequent development of coronary vasculitis." (PMID 36159873, 2022). "Marked activation of inflammatory cytokines including tumor necrosis factor-α (TNF-α) and interleukin (IL)-6 could be involved in the pathogenesis of myocarditis." (PMID 34926619, 2021). "Focusing on Immune response IFN-gamma signaling via MAPK that has been predicted by two different approaches that increased the confidence in this pathway map, highlighted two key biomarkers for myocarditis and antiviral immune processes: IFN-gamma and TNF-alpha." (PMID 34696294, 2021). "Myocarditis-NCV was classified as immune-mediated when anti-heart Abs were positive, viruses in cardiac tissue were absent, myocardial TLR-4 was overexpressed and inflammatory cytokines (IL-1β, IL-6, IL-8, TNF-α) in serum samples were elevated." (PMID 33355356, 2021). "However, the presence of TNF-α in the myocardium of chronically infected mice and humans suggests that besides controlling tissue parasitism, they may contribute directly or indirectly to the recruitment of inflammatory cells and the establishment of myocarditis." (PMID 34796122, 2021). "Specifically, TNF-α, but not IL-1 s, was essential for the development of acute-phase myocarditis, whereas IL-1 s were indispensable for the subsequent development of coronary vasculitis." (PMID 33023630, 2020). "In a mouse model of experimental autoimmune myocarditis induced by immunization with cardiac myosin, TNF-α/β neutralizing antibodies delivered prior to but not after immunization reduced the incidence of myocarditis." (PMID 33053859, 2020). "Similarly, digoxin blocked the lipopolysaccharide-stimulated secretion of IL-6, IL-8, and TNF-α from mononuclear cells, but promoted the expression of TNF-α and IL-6 in the heart of mice with myocarditis." (PMID 33101052, 2020). "Thus, Gr-1+ monocytes and macrophages other than neutrophils are the driving CD11b+ subsets mediating increased cardiac pathology including severe myocarditis and cardiac fibrosis in CVB3 infection by up-regulating TNF-α and TGF-β production in the heart." (PMID 29868513, 2018). "Both human KD patients and LCWE-treated mice developed coronary arteritis, myocarditis, valvulitis, and pericarditis, as well as elevated plasma levels of interleukin (IL)-2, IL-6, IL-10, monocyte chemoattractant protein (MCP)-1, and tumor necrosis factor (TNF)-α in acute phase." (PMID 22737215, 2012). "MSCs increased significantly the myocardial expression of HGF and decreased the expression of the proinflammatory cytokines TNFα, IL1β and IL6 as well as the severity of myocarditis and ameliorated the left ventricular dysfunction measured by conductance catheter." (PMID 22815907, 2012). "Since TNF-α and IFN-γ can increase endothelial CXCL9 expression, increased TNF-α and IFN-γ mRNA expression may have induced CXCL9 expression and facilitated myocarditis in the macaques that received CART." (PMID 21203448, 2010).
myocarditis (continued). "As the expression of chemoattractants is under the control of IFN-γ and TNF-α, it is possible that increased IFN-γ and TNF-α production, as a result of IL-17 neutralization and elevated IL-12 production, is responsible for the increased myocarditis." (PMID 20169058, 2010). "However, when both LAG-3 and PD-1 were lacking, a severe type of myocarditis developed that was marked by T-cell infiltration, increased production of tumor necrosis factor (TNF), and persistent Treg inhibitory activity." (PMID 40606990, 2025). "Therefore, we searched for studies focusing on TNF-α antibodies and other biological agents that were prescribed to patients with ICI-induced myocarditis, aiming to provide more clinical information for the selection of biological agents, time of intervention, efficacy and safety." (PMID 35844550, 2022). "If the cardiovascular risk of TNF-α inhibitors in ICI-induced myocarditis can not be eliminated, other biologic agents, such as abatacept, tocilizumab and alemtuzumab are promising, while data for their effects on ICI-induced myocarditis are still limited." (PMID 35844550, 2022). "It was recently found that TNF-induced PCD is considered deeply involved in the pathology and development of VMC that necroptosis may be a novel mechanism for cardiomyocyte death in the virus-induced acute myocarditis." (PMID 35602592, 2022). "We found that deguelin could efficiently decrease the expression of Akt1 and p-Akt but not Akt, Besides, deguelin increased the IL-1β, TNF-α expressions, aggravated the inflammation and fibrosis, therefore, deteriorated myocarditis." (PMID 32128091, 2019). "Thus, our data indicate that Gr-1+ cells may promote fibrogenesis and heart dysfunction in the CVB3 myocarditis model via increasing TGF-β and TNF-α-mediated inflammation while limiting IL-10 production." (PMID 29868513, 2018). "A role for TNF-α in VMC is supported by the recent findings that lack of TNF-a induction is a major factor in female resistance to VMC, exogenous TNF-a also makes normally CVB3 myocarditis-resistant female mice susceptible." (PMID 21235788, 2011). "Moreover, the treatment of acutely T. cruzi-infected mice with the anti-TNF antibody Infliximab did not impact heart parasitism but reduced fibronectin (FN) deposition in the heart and ameliorated cardiomyocyte lesion in association with reduced CD8-enriched myocarditis." (PMID 25140115, 2014). "The intensity of acute and chronic T. cruzi-elicited myocarditis is related to the concentrations of the CC-chemokines CCL3/MIP-1α and CCL5/RANTES, but not to the concentrations of IFNγ and TNF in the cardiac tissue." (PMID 22532799, 2012). "Interestingly, short treatment with Infliximab initiated three-month postinfection diminished cardiac TNF mRNA expression and CD8-enriched myocarditis in T. cruzi-infected rats, without evidence of parasitism reactivation but in presence of increased circulating IL-10 levels." (PMID 25140115, 2014).
fibrosis (159 papers, 2006 to 2026). the formation of excess fibrous connective tissue in an organ or tissue in a reparative or reactive process. "It was reported that activin A induces hepatic fibrosis by stimulating Kupffer cells (KCs) to secrete tumor necrosis factor (TNF)-α and TGF-β1, causing HSC activation." (PMID 38607090, 2024). "High IFN-γ levels are associated with a significant reduction in the risk of fibrosis, while high levels of TNF-α are associated with an increased risk of periportal fibrosis." (PMID 37887717, 2023). "TNF-α has been known to be significantly high in individuals with a higher risk of periportal fibrosis." (PMID 34239575, 2021). "TNF was linked to three toxicity-related lists generated by IPA: “Cardiac Fibrosis,” “Cardiac Hypertrophy” and “Cardiac Necrosis/Cell Death” and among them “Cardiac Hypertrophy” was shared between TNF and ESR1." (PMID 32903789, 2020). "Consistently, TNF-α played an important role in a porcine bronchial model of obliterative bronchiolitis with fibrosis, and its blockade was associated with decreased lesions." (PMID 26596627, 2015). "Functional characterization of PSMB8-AS1 in monocytes demonstrated that this lncRNA is involved in the secretion of IL-6 and TNFα, two pivotal pro-inflammatory cytokines altered in the circulation of SSc patients and associated with fibrosis and disease severity." (PMID 33922041, 2021). "However, they have been mentioned little of the EMT-associated Fibrotic Deposits, which is EMT-associated fibrosis by TNF-α and TGF-β2-treatment." (PMID 34727968, 2021). "Because pro-inflammatory cytokines such as IL-6 and TNF-α promote hepatic stellate cell activation and extracellular matrix deposition, cytokine dysregulation has been consistently associated with increased liver stiffness and higher non-invasive fibrosis scores in MASLD." (PMID 41470883, 2025). "Thus, it is likely that the loss of vasculatures caused by TNF inhibitors might lead to the degeneration and detachment of synoviocytes as well as the formation of discoid fibrosis in the sublining layers." (PMID 23575549, 2013). "The immune response is also implicated, pro-inflammatory diets activate the immune system, increasing cytokine production such as TNF-α and IL-6, which further aggravate liver damage and fibrosi." (PMID 40242166, 2025). "Anthropometric data, lipid profile, glycemic markers, cytokines (IL-6, IL-10, TNF-α), liver stiffness, and non-invasive fibrosis indices were compared across groups using standard statistical testing." (PMID 41470883, 2025). "Among them, we can mention TGF-β, whose levels correlate with the presence of fibrosis either in ALD or in HCV patients and TNF-α, which correlates with fibrosis in ALD and HBV patients." (PMID 39201990, 2024). "Inflammatory cytokine levels (e.g., IL-6, IL-8, IL-10, TNF-α, and IFN-γ) in the synovial fluid are not only increased, but also correlate with IPFP fibrosis and have been associated with poorer clinical outcomes (e.g., Lysholm score)." (PMID 38549837, 2024). "Second, in various animal fibrosis models, ketanserin was shown to decrease the levels of several cytokines such as TNF-α, IL-10, IL-1β, IL-8, and IL-633,35,36." (PMID 38228622, 2024). "In experimental models, the presence of serpine 1 is probably increased via transforming growth factor-β and tumor necrosis factor-α, and participates in cardiac fibrosis and ventricular remodeling." (PMID 37958681, 2023). "The classic pro-inflammatory cytokines IL-6, IL-1β, and TNF-α have the effect of promoting fibrosis, which has been observed in fibrosis models of lung, heart, kidney." (PMID 37305520, 2023). "In IPF patients, activated macrophages and TNF-α production play critical roles in the progression of pulmonary inflammation and/or fibrosis." (PMID 37773193, 2023).
fibrosis (continued). "According to our data, GSEA also showed that fibroblasts in the defunctioned intestine were enriched of inflammatory and fibrosis‐related signalling pathways (e.g. defective CFTR causes cystic fibrosis and TNF‐mediated signalling pathway)." (PMID 37400975, 2023). "We postulate that sterile inflammation, including the release of TNFα, IL-1β, IL-18 and IL-6, leads to changes in the endothelial-epithelial barrier and induces chronic fibrosis." (PMID 36993804, 2023). "In the present study, the results showed that activin A promoted the secretion of TGF-β1 in L929 cells, while TNF-α inhibited the production of TGF-β1 induced by activin A. Fibrosis involves a dynamic balance between the biosynthesis and degradation of ECM." (PMID 33244088, 2020). "IL-5also plays an important role in promoting tissue fibrosis; and TNF antagonists are beneficial for the treatment of fibrotic disorders, supporting a pro-fibrotic role of TNF." (PMID 31878218, 2019). "We also measured the expression of M1 macrophage-related inflammatory factors including IFN-γ, TNF-α, and IL-6 in liver tissue, which simultaneously increased in the fibrosis group but obviously decreased in the fibrosis+MSC group." (PMID 30635047, 2019). "It was reported that Smad3KO mice inhibit cardiac fibrosis, decreasing the expression of αSMA, TGFβ1, and TNFα." (PMID 31597354, 2019). "The current results revealed that there was a significant decrease in TNF gene levels in the groups treated by MSCs, neupogen, and MSCs + neupogen compared with the untreated fibrosis group." (PMID 28883083, 2017). "Previous studies have shown that elevated TNF-α levels are an independent predictor of histological fibrosis in patients with NAFLD." (PMID 27560482, 2016). "The content of TGF-β1 (up to 5033%) and IL-1β (up to 541%) in serum of mice with fibrosis on 3rd day of experiment was higher than that of serum from healthy mice, however the concentration of TNF-α was reduced (to 38%) compared with healthy mice." (PMID 25927611, 2015). "Measuring IL-1β, IL-18, CTGF, and TNF-α in BAL fluid along with pulmonary function tests may enable early diagnosis of patients who will develop fibrosis." (PMID 41302962, 2025). "Most interestingly, a mouse model of bleomycin-induced fibrosis showed that the administration of human CCL18 via an adenoviral vector increased TNF-, IFNγ-, MMP-2 and MMP-9 expression and increased lymphocytosis but attenuated unexpectedly the bleomycin-induced collagen deposition." (PMID 38334630, 2024). "Apart from its possible role in the pathogenesis of NAFL, TNF-α may play a more substantial role in the pathogenesis of NASH and NAFLD-associated fibrosis." (PMID 37407724, 2023). "Similar changes in active TGF-β1 and TNF-α were observed in asbestos-induced fibrosis." (PMID 34413485, 2022). "Previous studies revealed that TMAO may exacerbate cardiac fibrosis and inflammation induced by high glucose levels via upregulating the proinflammatory cytokines TNF-α and IL-1β." (PMID 31354519, 2019). "TNF-a is involved in the regulation of hepatic fibrosis through a variety of mechanisms." (PMID 28358817, 2017). "Thus, it can be said these two relevant cytokines (TGF-β1 and TNF-α) contribute to airway fibrosis because of their ability to regulate fibroblast and matrix production." (PMID 23997916, 2013). "Observations that soluble TNF-α receptor treatment improved the outcome following acute CCl4-intoxication, and that monoclonal antibodies against TNF-α improved experimental CCl4-induced fibrosis led us to explore the involvement of TNF-α and TACE in CCl4-mediated hepatotoxicity." (PMID 20593020, 2010). "Moreover, we found that Kdm4a increases the expression of SASP factors from premature senescent fibroblasts, then accelerating interstitial fibrosis through various classic fibrosis‐associated pathways, including ECM‒receptor interactions, the TGF‒β signaling pathway, and the TNF signaling pathway." (PMID 40231733, 2025).
fibrosis (continued). "In addition, higher circulating TNF-α levels in patients with than without NAFLD-associated fibrosis were also reported in this study; however, this finding should be carefully interpreted, because only two studies were included in this subgroup comparison." (PMID 37407724, 2023). "The chemokine signaling pathway, adrenergic signaling in cardiomyocytes, TNF signaling pathway, and the advanced glycation end products (AGEs)- receptors for AGEs (RAGE) pathway (which is involved in diabetic complications) also appear to be important mechanisms associated with cardiac fibrosis." (PMID 34368154, 2021). "We hypothesized that blocking TNF-α may be of interest in management of post-operative peridural lumbar fibrosis, and we aimed to assess the efficacy and safety of TNF-α inhibition with infliximab (IFX) on the associated sciatica pain 10 days after the treatment." (PMID 26596627, 2015). "To further investigate the impact of AS/LIG/AS_LIG@PPGC NPs on pulmonary inflammation and fibrosis in IPF, we collected mouse BALF on Days 8 and 22 and measured the levels of IL-1β, IL-6, TNF-α, and TGF-β1 using ELISA." (PMID 38166847, 2024). "For example, the expression of tumor necrosis factor-alpha (TNF-α) was upregulated in bleomycin-induced mouse lung tissue, whereas mice with TNF-α receptor knockout exhibited protection from asbestos-induced fibrosis." (PMID 37986064, 2023). "Fibrosis is the result of chronic inflammatory reactions, and FAT10 increases inflammation by increasing TNF-α/IFN-γ and NF-κB and STAT3 pathways, all of which were up regulated in fibrosis patients." (PMID 36386217, 2022). "In one study of bleomycin-induced fibrosis in mice, MSC improved survival by diminishing TNF-α, TGF-β1, and LOX levels, and finally the inflammation process in IPF." (PMID 36588784, 2022). "For instance, there is a significant increase in levels of pro-inflammatory cytokines such as TNF-α and IL-8 in the lungs of patients with IPF, and TNF-α has been shown to be important in bleomycin-induced fibrosis." (PMID 35559024, 2022). "The serum TNF-α and IL-6 levels in the NAFLD group decreased after drug intervention, while in the GXZY-NASH and GXZY-fibrosis groups, SOD levels increased, MDA expression decreased, and the oxidative stress response was inhibited." (PMID 34887931, 2021). "Fibrosis, histopathological features, serum creatinine (sCr), BUN, and renal mRNA expression of αSMA, Col-1α, TGF-β1, CTGF, BMP7, IL-1, TNFα, VEGF and PAX2 were analyzed." (PMID 33275619, 2020). "Levels of TNF-α, MDA, NO, and ONOO- in the lung homogenate were significantly increased in the fibrosis model group." (PMID 33817199, 2019). "TNF-α and MCP-1 showed a downward trend towards lower expression levels compared to vehicle in the fibrosis study." (PMID 30467325, 2018). "Consistent with the literature, we found that the expression levels of IL-6, TNF-α and TGF-β1, triggering the activation of HSCs, were decreased significantly in the liver tissues of the IDO1–/– fibrosis mice." (PMID 28465467, 2017). "Our results demonstrated that hepatic expression of TNF-α, IL-1β, and MCP-1 mRNA was strongly upregulated in BDL fibrosis models." (PMID 28744285, 2017). "PegHYAL was reduced the concentration of TNF-α (to 1.3%), IL-1β (to 72%), TGF-β1 (to 12.5%) in serum and TGF-β (to 11%) in BLM-injured lung compared to untreated mice with fibrosis." (PMID 25927611, 2015). "In this double-blind, randomized controlled trial, we assessed the efficacy and safety of TNF-α blockade with a single intravenous injection of IFX, 3 mg/kg, in managing sciatica pain due to post-operative peridural lumbar fibrosis." (PMID 26596627, 2015). "The subsets of monocytes from individuals with different degrees of periportal fibrosis were evaluated regarding the expression of the profibrotic markers such as IL-4Rα and TGF-β and proinflammatory cytokines such as IL-6 and TNF-α." (PMID 24757288, 2014).